GAGE12E (G antigen 12E)
Synonyms: GAGE-12B; OTTHUMG00000024146
Gene: Protein-coding gene on chromosome X (49,551,289 to 49,558,645, forward strand). Ensembl gene ENSG00000216649.
Subcellular location (Human Protein Atlas): Plasma membrane; Cytosol; Golgi apparatus
Gene Ontology:
Molecular function: protein binding
Homologues: Orthologues: chimpanzee GAGE10 (82% identical). Paralogues in human: GAGE12C (100% identical), GAGE12D (100% identical), GAGE12F (99% identical), GAGE12G (99% identical), GAGE12H (99% identical), GAGE1 (97% identical), GAGE12J (97% identical), GAGE13 (97% identical), GAGE2A (96% identical), GAGE2E (93% identical), GAGE10 (90% identical), PAGE1 (52% identical), and 10 more.
Diseases named in the same sentence as GAGE12E in open-access papers:
GAGE12E is named in the same sentence as 1 disease in open-access papers, as found by Europe PMC text mining. Sharing a sentence is not in itself a finding about the gene and the disease. The quoted sentences say what the papers report.
tumor (1 paper, 2024). "For instance, GAGE12E, a crucial member of the cancer–testis antigen family, is associated with tumor immunity." (PMID 39199384, 2024).